ERBB4 (erb-b2 receptor tyrosine kinase 4)
Diseases named in the same sentence as ERBB4 in open-access papers (continued):
Sharing a sentence is not in itself a finding about the gene and the disease.
schizophrenia (continued). "This study investigates the effects of aripiprazole and sertindole on the NRG1/ErbB4 and PI3K/AKT/mTOR signaling pathways in ketamine-induced schizophrenia in rats." (PMID 35876932, 2022). "Patients with schizophrenia have disturbances in neuregulin-1 (NRG1) and its receptor tyrosine kinase ErbB4." (PMID 33552387, 2021). "Another possibility is that NMDAR deficiency in PV and possibly ErbB4 neurons may be a risk factor for developing schizophrenia, but is not sufficient on its own: environmental risk factors or other supplementary triggers may be needed to lead to clinical manifestation." (PMID 34899420, 2021). "As reviewed here, some of the genetic animal studies, such as NRG1/ErbB4 and 14-3-3 animal models, provided evidence to support NMDAR hypofunctionality as a potential convergence point for symptoms of schizophrenia." (PMID 31417356, 2019). "A post-mortem study of schizophrenia found elevated NRG1 and ErbB4 proteins in the prefrontal cortex." (PMID 30574102, 2018). "Indeed, the deletion of ErbB4 in fast-spiking interneurons, which include Ch cells, has been shown to elicit a plethora of functional deficits that may be related to the pathophysiology of schizophrenia." (PMID 25056931, 2015). "The gain and loss of function of Nrg1/ErbB4 signaling were examined because postmortem studies of schizophrenia reported both increased and decreased NRG1/ERBB4 signaling in schizophrenic patients." (PMID 25805966, 2015). "Nevertheless, given the fact that the NRG1 – ERBB4 signaling has multiple effects in nervous system development (including neuronal migration and modulation of neurotransmission), this pathway may play a role in schizophrenia pathogenesis through other mechanisms aside from OMR effects." (PMID 24478629, 2014). "For example, studies of schizophrenia have revealed synergistic SNP-SNP interactions in dopamine receptor D4 (DRD4) and in neuregulin 1 (NRG1)/v-erb-a erythroblastic leukemia viral oncogene homolog 4 (avian) (ERBB4)/AKT1 genes." (PMID 24955105, 2014). "More evidence suggests that ErbB4 exerts its effects on PV-positive interneurons: PV-ErbB4-/- mice exhibit a schizophrenia-like phenotype much like that of NRG1-null and ErbB4-null mutants; these mice are hyperactive and show impaired working memory." (PMID 23618463, 2013). "ZFHX3, RND3, KLF5, ERBB4, EGR1 and APC genes are both schizophrenia candidate genes and tumor suppression genes." (PMID 24564241, 2013). "Thus, this study aimed to investigate the effects of aripiprazole and sertindole on the NRG1/ERbB4 and PI3K/AKT/mTOR signaling pathways in ketamine-induced schizophrenia in rats." (PMID 35876932, 2022). "The NRG1/ERbB4 and PI3K signaling pathways may offer a new therapeutic approach to developing treatment for schizophrenia in humans, which needs to be assessed in further studies." (PMID 35876932, 2022). "The lncRNA GOMAFU can change the AS events of schizophrenia-related genes DISC1 and ERBB4, and GOMAFU can interact with splicing factors QKI and SRSF1, which may be the mechanism of GOMAFU participating in the AS process." (PMID 34750493, 2022). "The NRG1/ErbB4 and PI3K signaling pathways may offer a new therapeutic approach for treating schizophrenia in humans." (PMID 35876932, 2022). "Here we report that ablation of GluN1-containing NMDAR in ErbB4 expressing cells in adults mice does not significantly affect cognition and does not induce the typical behavioral correlates of schizophrenia, depression and anxiety." (PMID 34899420, 2021). "An interesting and important aspect of our findings of DA imbalance in ErbB4 and NRG2 KO mice, regardless of the underlying mechanisms, is that they are reminiscent of the DA imbalance reported in schizophrenia patients." (PMID 32354758, 2020).
schizophrenia (continued). "As GOMAFU was found to be downregulated in post-mortem cortical tissue from the superior temporal gyrus of schizophrenia patients, the aberrant splicing patterns of DISC1 and ERBB4 in schizophrenia are suggested to be a consequence of disturbed GOMAFU expression." (PMID 31698782, 2019). "For example, genes involved in the neuregulin 1–ErbB4 signaling pathway, including DOCK7, EGFR, PTPRZ1 and the key regulator ERBB4,45, 46, 47 were downregulated in undifferentiated and disorganized schizophrenia, while they were upregulated in paranoid schizophrenia." (PMID 28809853, 2017). "Since the dendritic length of interneurons is reduced in schizophrenia, understanding how NRG1/ErbB4 signaling regulates the dendrites of these cells may help clarifying the mechanisms underlying the cortical defects in this disorder." (PMID 25309333, 2014). "Additionally, phosphorylation of Erbb4 by NRG1 and downstream AKT and ERK2 signalling are more likely to be activated in schizophrenia, compared to control samples." (PMID 23301017, 2013). "NRG1 and its cognate receptor ErbB4 regulate the development of activity-driven glutamatergic synapse development, indicating that NRG1 signalling may contribute to schizophrenia pathophysiology in the context of the glutamate hypothesis of schizophrenia." (PMID 29467679, 2018). "The results showed the top five associated SNPs with CSS of ERBB4, NRG1 and COMT respectively, while none of the SNPs of schizophrenia associated genes COMT, ERBB4 or NRG1 was satisfied the criteria of GWAS significance threshold (Bonferroni correction P < 0.05/498,648, or i.e., ~1.0 × 10−7)." (PMID 26242244, 2015). "Indeed, a large deletion (∼400 kb) of the 3′region of ERBB4 has been reported in a subject with schizophrenia, but, toour knowledge, no study has performed comprehensive sequencing ofERBB4." (PMID 21637803, 2011). "Decreased spine density in hippocampal pyramidal neurons was also observed in Bace1-/- mice via NRG1/ErbB4 signal pathway regulation, suggesting that disturbed NRG1/ErbB4 signaling pathways in the Bace1-/- mouse model may contribute to the pathophysiology of schizophrenia." (PMID 28993723, 2017). "Moreover, in genome-wideassociation studies (GWAS) of Caucasians with schizophrenia or bipolar disorder,neither NRG1 nor ERBB4 have featured among the tophits in the original studies or in subsequent meta-analyses." (PMID 21637803, 2011).
melanoma (55 papers, 2011 to 2025). A malignant, usually aggressive tumor composed of atypical, neoplastic melanocytes. "The proliferation of melanoma cells harboring mutant ERBB4 is driven by the ERBB4 signaling pathway, and inhibition of this protein causes melanoma cell death." (PMID 39340537, 2024). "As a result, there is a scarcity of dedicated clinical studies investigating targeted therapies for ERBB4-mutated melanoma." (PMID 37504268, 2023). "ERBB4 is found to be somatically mutated in 19% of melanomas, with the majority of alterations occurring in the extracellular domain of the receptor, resulting in enhanced kinase activity." (PMID 37181747, 2023). "Recent findings show that the prevalence of ERBB4 mutations in melanoma is relatively low compared to other genetic alterations like BRAF or NRAS mutations." (PMID 37504268, 2023). "The most common specific somatic mutations in ERBB4 in melanoma are usually point mutations, which are changes to a single nucleotide (a building block of DNA) in the gene’s sequence." (PMID 37504268, 2023). "Genes from the RTK/PI3K pathway, including PTEN, PIK3R1 in glioma, and ALK, PIK3C2G, ERBB4 in melanoma, showed lower mutation rates in AYAs, reiterating our earlier observation on recurrent genes." (PMID 36433963, 2022). "ErbB4 gain-of-function mutations are believed to be used by melanoma cells to activate the PI3K pathway." (PMID 36119496, 2022). "Taken together, these data indicate that ERBB4 mutations appear to function as tumor drivers in BRAF wild-type melanomas by cooperating with elevated RAS signaling." (PMID 33378376, 2020). "Mutations in the ERBB4 gene—which encodes HER4—were associated with oncogenic gain-of-function effects in human melanoma." (PMID 31996230, 2020). "Our ongoing, unpublished analyses of the TCGA skin cutaneous melanoma genomic (SKCM) data set reveal that 70 of the 470 (15%) of the melanoma genomes harbor at least one non-synonymous missense mutation in the ERBB4 gene." (PMID 33378376, 2020). "For instance, lapatinib is already under clinical trial in patients with stage IV melanoma with ERBB4 mutations." (PMID 30301885, 2018). "In melanoma, ERBB4 mutations have been shown to be the major oncogenic driver with both aberrant ERBB4 and PI3K-AKT signaling." (PMID 30301885, 2018). "Mutation analysis of protein tyrosine kinases identified some recurrent mutations in ERBB4 (19% of melanomas) and Fms related Tyrosine Kinase 1 (FLT1) and Protein Tyrosine Kinase 2 Beta (PTK2B) (10% of melanomas)." (PMID 29156643, 2017). "ERBB4 has been shown to be highly mutated in melanoma, where ERBB4 mutations increase ERBB4 kinase activity despite similar expression of the HER4 protein and sensitise cells to lapatinib." (PMID 28750640, 2017). "According to the TCGA, the percentage of tumors with putative ERBB4 driver mutations are highest in melanoma and esophagogastric, followed by endometrial cancer, colorectal cancer, and NSCLC." (PMID 29371993, 2017). "In malignant melanoma, activating mutations in ERBB4 have been identified in 19% of melanoma patients." (PMID 26745281, 2016). "ErbB4 mutations have been described to occur in lung, breast, gastric cancer and melanoma and like for ErbB3 differ from those observed in EGFR or HER2 by not displaying characteristic mutational hotspots." (PMID 24643470, 2014). "Nevertheless, lapatinib, a reversible inhibitor of EGFR, ERBB2, and other kinases is currently in a clinical trial for advanced melanoma with ERBB4 mutations (NCT01264081)." (PMID 24743024, 2014). "In a genome wide search of the tyrosine kinome, ERBB4 mutations were identified in 19% of patients with melanoma." (PMID 22385436, 2012). "A phase 2 trial of lapatanib in stage IV melanoma patients who harbor an ERBB4 mutation is currently enrolling." (PMID 22385436, 2012).
melanoma (continued). "The role of ErbB3 in melanoma can also be indirectly inferred from the evidence that driver mutations are found in ErbB4, its preferred heterodimerizing partner in these cells, in a significant percentage of melanomas (approximately 20%)." (PMID 22889873, 2012). "Significantly, a recent report identified activating mutations in the same cysteine rich region of ErbB4 in melanoma." (PMID 24212795, 2011). "Clinically, ErbB4 somatic mutations have been detected in 19% of melanoma patients and in a variety of other cancer types although at a much lower frequency (1–5% reviewed by Rudloff and Samuels, 2010)." (PMID 21364581, 2011). "The mutation rate of ERBB4 in melanoma is 19% and there is one ”mini-hotspot” (E452K)." (PMID 39340537, 2024). "ERBB4 gene has been found to be mutated in a variety of cancer types, including melanoma." (PMID 37504268, 2023). "However, a phase II clinical trial evaluating the safety and efficacy of lapatinib in treatment refractory stage IV melanoma patients carrying ERBB4 mutations (NCT01264081) was terminated with 30/34 patients failing to complete the trial." (PMID 37181747, 2023). "Importantly, ERBB4 mutations increased the ability of melanoma cells to grow under anchorage-independent conditions, as assessed by the ability of SK-MEL-2 cells to form colonies in soft agar." (PMID 37181747, 2023). "Similarly, novel ErbB4 mutations are present in 19% of melanoma patients and seven missense mutations in ERBB4 have been found to increase transformation ability and kinase activity." (PMID 36119496, 2022). "In melanoma cells resistant to trametinib, few damaging mutations were found including L437F and K438M substitutions in ERBB4 in 11_TRAR, G388R variant of FGFR4, and E36A variant of platelet-derived growth factor receptor alpha (PDGFRA) in 21_TRAR, and E519K alteration of RASGRP4 in 17_TRAR cells." (PMID 31936151, 2020). "Furthermore, ERBB4 somatic mutations identified in melanoma increase ERBB4’s kinase activity and capacity to transform cell lines." (PMID 30044378, 2018). "ERBB4 mutations have been identified in lung, breast and gastric cancer and melanoma." (PMID 27844328, 2017). "Several of these ERBB4 mutations were shown to be oncogenic in melanoma models and could be inhibited by treatment with lapatinib." (PMID 27844328, 2017). "Several of these ErbB4 mutations were shown to be oncogenic in melanoma models." (PMID 24643470, 2014). "In vitro depletion of ErbB4 in some melanoma cell lines expressing mutated ErbB4 inhibited proliferation, suggesting that mutated ErbB4 may be an addicting oncogene in these particular cells." (PMID 21364581, 2011). "Thus, mutated ERBB4 is a potential therapeutic target in melanoma treatment." (PMID 39340537, 2024). "Moreover, variants in the ERBB4 gene, a commonly mutated proto-oncogene in melanoma, were detected in higher numbers in HP compartments (1, 5, 2, and 1 variant in Patients 2–4, respectively) than in LP compartments (0, 4, 3, and 0 variant in Patients 2–4, respectively)." (PMID 33918692, 2021). "Compounds that exhibit these characteristics likely function as ErbB4 partial agonists, and as such hold promise as therapies for ErbB4-dependent melanomas." (PMID 33378376, 2020). "STAT3 is a critical point of convergence downstream of several hyperactive tyrosine kinase receptors that are either mutated or amplified in melanoma, such as KIT, ERBB4, EPH, FGFR, EGFR and PDGRFA, among others." (PMID 33396645, 2020). "The protein expression of ERBB1 and ERBB4 in the TPF-3-84 melanoma isolate was similar to the expression levels found in the TPF-14-405, TPF-15-232 and TPF-16-76 isolates." (PMID 29464055, 2018). "This technique has been applied within a clinical trial to select patients with ERBB4-mutant melanoma for lapatinib treatment." (PMID 29371993, 2017).
melanoma (continued). "Malignant transformation of melanomas is accompanied by loss of KIT and acquisition of EPO-R and ErbB4, both of which are co-expressed with NGF-R and PD-1 in distinct subfractions of melanoma cells." (PMID 24489649, 2014). "ERBB4, which encodes the tyrosine kinase receptor HER4, has varied effects on cancer development, but mutations in this gene have been implicated in several neoplasms, including melanoma, lung carcinoma and stomach carcinoma." (PMID 39435876, 2024). "Two studies suggested that ERBB4 is disorder in melanoma, and ERBB4 kinase inhibition may constitute an effective therapeutic strategy." (PMID 36167504, 2022). "The variant ERBB4 c.2513G>A is described in the COSMIC database as pathogenic (score 0.99) and has already been observed in hormone receptor-positive breast cancer, large bowel adenocarcinoma, malignant melanoma, and gastroesophageal junction adenocarcinoma." (PMID 33503190, 2021). "In this chapter, we found that ERBB4 is the highest mutation rate in the ERBB family, but it may not impact the tumor stage, disease-free survival, and 5 years survival rates of melanoma patients." (PMID 33732282, 2021). "This suggests it may be possible to treat ErbB4-dependent melanomas using anti-EGFR and -ErbB2 therapies, particularly small molecule EGFR and/or ErbB2 tyrosine kinase inhibitors." (PMID 33378376, 2020). "Consequently, we believe that compounds that function as partial agonists of ErbB4 hold great promise for the treatment of ErbB4-dependent melanomas." (PMID 33378376, 2020). "Therefore, the discovery of strategies for inhibiting ErbB4 coupling to melanoma cell proliferation is a priority." (PMID 33378376, 2020). "Moreover, subsequent studies showed that the percentage of ERBB4-mutated samples was indeed much lower in an independent cohort (around 3%), and the higher percentage found in the first study might have been due to a sampling bias of melanoma cell cultures versus melanoma tissues." (PMID 30987166, 2019). "In ERBB4-mutant melanomas, mutant ERBB4 expression is required to sustain melanoma growth." (PMID 29156643, 2017). "The GENIE database indicates that ERBB4 driver mutations are most common in skin non-melanomas, but are also found in melanomas, endometrial cancers, bladder cancers, colorectal cancers, NSCLC, and esophagogastric cancers." (PMID 29371993, 2017). "Another cytokine receptor detectable in a distinct subpopulation of melanoma cells was ErbB4." (PMID 24489649, 2014). "Finally, we were able to show that this EPO-R+/CD24+/ErbB4+ subpopulation of melanoma cells co-expresses the putative melanoma stem cell antigen PD1 as well as the NGF-R (CD271)." (PMID 24489649, 2014). "Subsequent studies have reported either much lower incidence (2% of 271 tumors) of ERBB4 mutations in melanoma, or lack of any in sampling of 117 tumors." (PMID 24743024, 2014). "Together, our data suggest that malignant transformation in melanomas may be associated with loss of KIT and expression of EPO-R and ErbB4." (PMID 24489649, 2014). "Therefore, inhibition of ErbB3 with monoclonal antibodies is expected to impair the growth promoting effect of mutant ErbB4-ErbB3 heterodimers in melanomas." (PMID 22889873, 2012). "Moreover, the SP‐01 tumor presents an activating mutation in the ERBB4 gene, which is described as a driver of BRAF wild‐type (WT) melanomas, and SP‐06 presents an oncogenic NRAS mutation, inactivation of NF2, and a truncating mutation in SMARCA4 (in one allele)." (PMID 37798904, 2024). "Moreover, this subpopulation of melanoma cells co-expressed ErbB4." (PMID 24489649, 2014). "ERBB4 is a member of the EGFR family, which is known to play a role in experimental melanoma models." (PMID 30987166, 2019). "Genes where a statistically significant difference in mutation rate was observed were APC (p = 9 × 10−7) in CRC, STK11 (p = 0.008) in NSCLC, and CDKN2A (p = 0.02), ERBB4 (p = 9 × 10−4), FLT3 (p = 0.02), and KDR (p = 0.01) in melanoma." (PMID 28196074, 2017).
melanoma (continued). "All in all, melanoma cells display a unique composition of cytokine receptors and differ from normal melanocytes in expression of EPO-R, ErbB4, and KIT." (PMID 24489649, 2014). "We also found that in most patients, distinct subfractions of melanoma cells co-express EPO-R, CD24, and ErbB4, and that EPO-R expression overlaps with NGF-R expression." (PMID 24489649, 2014). "In most patients, a distinct subpopulation of melanoma cells (4–40%) expressed the erythropoietin receptor (EPO-R) and ErbB4 together with PD-1 and NGF-R/CD271." (PMID 24489649, 2014). "We demonstrated moderate decreases in ERBB4 activity by treatment with Lapatinib, a pan-ERBB inhibitor previously used to target ERBB4 in melanoma." (PMID 23681745, 2013). "Treatment with lapatinib was demonstrated to significantly reduce cell growth in ERBB4-mutant melanoma cells lines at 10- to 250- fold higher sensitivity (IC50) than ERBB4 WT cells, resulting in dose-dependent inhibition of ERBB4 auto-phosphorylation and downstream Akt signalling." (PMID 37181747, 2023). "Melanoma cells derived from the primary and secondary recipients were found to express the same phenotype when compared to the initial melanoma sample, including the EPO-R as well as ErbB4 and CD24, although expression of NGF-R was very low." (PMID 24489649, 2014). "In most donors, subpopulations of melanoma cells also expressed the EPO-R, CD24, and ErbB4." (PMID 24489649, 2014). "However, expression of EPO-R/ErbB4/PD-1 is not indicative of a selective melanoma-initiating potential." (PMID 24489649, 2014). "While other genes (e.g. CDKN2C, CDKN2A, MITF, BAP1, PTEN, ERBB4, and FGFR2, etc.)are mutated with some frequency in melanoma, no common recurring mutations in these genes are observed or the function of observed mutations are unknown; therefore these genes were not included in our screen." (PMID 22536370, 2012).